PRG4 (proteoglycan 4)
Description:
Plays a role in boundary lubrication within articulating joints. Prevents protein deposition onto cartilage from synovial fluid by controlling adhesion-dependent synovial growth and inhibiting the adhesion of synovial cells to the cartilage surface. Isoform F plays a role as a growth factor acting on the primitive cells of both hematopoietic and endothelial cell lineages.
Synonyms: MSF; SZP; JCAP; HAPO; bG174L6.2; FLJ32635; CACP
Tractability: Antibody: UniProt places it where antibodies can reach, with high confidence; UniProt predicts a signal peptide or a membrane-spanning region; its Gene Ontology location is reachable by antibodies, with medium confidence. PROTAC: ubiquitination databases record sites on it; its protein half-life has been measured.
Gene: Protein-coding gene on chromosome 1 (186,296,270 to 186,314,567, forward strand). Ensembl gene ENSG00000116690.
Subcellular location: Secreted
Gene Ontology:
Molecular function: extracellular matrix structural constituent conferring compression resistance; polysaccharide binding; scavenger receptor activity
Biological process: immune response; vesicle-mediated transport
Cellular component: extracellular matrix; extracellular region
Genetic constraint (gnomAD): Loss-of-function variants: 59 observed, 91.44 expected, observed/expected ratio (o/e) 0.65, 90% interval 0.52 to 0.8. The upper end of that interval is the gene's LOEUF score, 0.8, which puts it in group 3 of 6, group 1 being the genes least tolerant of losing a copy. Missense variants: 1,529 observed, 1,715.1 expected, observed/expected ratio (o/e) 0.89, 90% interval 0.85 to 0.93. Synonymous variants: 562 observed, 589.27 expected, observed/expected ratio (o/e) 0.95, 90% interval 0.89 to 1.02.
Gene-disease validity (ClinGen):
ClinGen rates the evidence that PRG4 causes each of these diseases.
camptodactyly-arthropathy-coxa vara-pericarditis syndrome (autosomal recessive): Definitive.
Homologues: Orthologues: macaque PRG4 (85% identical), rat Prg4 (67% identical), mouse Prg4 (63% identical), dog PRG4 (53% identical), tropical clawed frog prg4 (22% identical), zebrafish prg4b (17% identical), zebrafish prg4a (11% identical). Paralogues in human: VTN (9% identical).
Diseases named in the same sentence as PRG4 in open-access papers:
PRG4 is named in the same sentence as 71 diseases in open-access papers, as found by Europe PMC text mining. Sharing a sentence is not in itself a finding about the gene and the disease. The quoted sentences say what the papers report.
osteoarthritis (42 papers, 2006 to 2026). A noninflammatory degenerative joint disease occurring chiefly in older persons, characterized by degeneration of the articular cartilage, hypertrophy of bone at the margins and changes in the synovial membrane. "It significantly increases the number of apoptotic cells and causes the loss of the superficial zone along with a decrease in Prg4 expression, highlighting β-catenin’s key role in cartilage integrity and osteoarthritis pathogenesis." (PMID 40149669, 2025). "The presence of PRG4+ fibroblasts and their association with disease activity in osteoarthritis and rheumatoid arthritis underscores the importance of understanding the roles of specific fibroblast subtypes in disease progression." (PMID 38002046, 2023). "Altered expression and function of PRG4 have been associated with joint inflammatory diseases, including osteoarthritis." (PMID 37024468, 2023). "In the present study, chondrocytes stimulated with IL-1β exhibited downregulation of COL2A1 and upregulation of MMP13, Prg4, Sulf1, Adam10, and Fstl1, supporting that enhanced inflammation is a critical mechanism underlying the progression of osteoarthritis." (PMID 37525533, 2023). "Altered expression and function of the extracellular matrix protein PRG4 have been associated with osteoarthritis." (PMID 37024468, 2023). "In recent years, abnormal expression of PRG4 has been associated with joint diseases such as osteoarthritis (OA) and rheumatoid arthritis (RA), and changes in PRG4 expression have been attributed to biological and mechanical stimuli." (PMID 36680176, 2022). "After the onset of early osteoarthritis, we demonstrated a loss of cellular proteoglycan 4 immunostaining in degenerative articular cartilage, accompanied by a significant (p < 0.01) decrease in corresponding mRNA levels." (PMID 16469119, 2006). "In vivo pre-clinical animal studies and ex vivo studies on human tissues have demonstrated that altered expression and function of PRG4 (i.e. diminished lubrication and increased inflammation) has been associated with joint damage and pain in osteoarthritis (OA) and RA." (PMID 34950038, 2021). "Moreover, PRG4 deficiency has also been implicated in the pathogenesis of osteoarthritis, thus making this an attractive candidate gene for further study." (PMID 18433489, 2008). "Early loss of proteoglycan 4 from the cartilage surface in association with a decrease in its expression by superficial-zone chondrocytes might have a role in the pathogenesis of osteoarthritis." (PMID 16469119, 2006). "PRG4 synovial fibroblasts secrete R-spondin-2 to promote the occurrence and development of osteoarthritis." (PMID 40470275, 2025). "Studies utilizing animal models of post-traumatic osteoarthritis have demonstrated the downregulation of Prg4 following joint injury, which results in increased cartilage friction and accelerated degeneration." (PMID 40149669, 2025). "Here we show that tryptase β as a modulator of joint lubrication in osteoarthritis via the cleavage of PRG4." (PMID 37024468, 2023). "In the destabilization of the medial meniscus model of osteoarthritis in rat, tryptase β and PRG4 colocalize at the site of injury in knee cartilage and is associated with disease severity." (PMID 37024468, 2023). "In diseases like osteoarthritis, hyaluronan and PRG4 concentrations can be altered, resulting in lowered synovial fluid viscosity, and pro-inflammatory cytokine concentrations within the synovial fluid increase." (PMID 36576921, 2022). "In this study, mice lacking the orthologous gene Prg4 served as a model that recapitulates the destructive arthrosis that involves biofouling of cartilage by serum proteins in lieu of Prg4." (PMID 35457064, 2022). "In contrast, Prg4-Cre-driven stabilization of β-catenin enhances resistance against osteoarthritis, as well as expression of the Prg4 gene in the superficial zone of articular cartilage." (PMID 32754592, 2020).
osteoarthritis (continued). "For the horse, changes to proteoglycan-4 concentration and function are notable in acute joint injury and osteoarthritis." (PMID 33392293, 2020). "This study provides further insight into the nature of cartilage boundary lubrication and advancement towards potential formulation of new intra-articular biotherapeutic treatments for osteoarthritis using PRG4 ± HA." (PMID 26666513, 2015). "A shift in lubricin expression from the SFZ to the intermediate zone was noted in patients with osteoarthritis, and an intra-articular injection of PRG4 attenuated cartilage damage and reduced inflammation in a porcine model of posttraumatic osteoarthritis (OA)." (PMID 38891793, 2024). "Prg4+ synovial fibroblasts expressed Rspo2, which may contribute to pathological crosstalk between joints in the post-traumatic osteoarthritis model." (PMID 38002046, 2023). "In addition, upregulating genes such as Prg4 and A2m can effectively inhibit the progression of osteoarthritis." (PMID 37993861, 2023). "When human primary synovial fibroblasts from male osteoarthritis patients or male healthy subjects treated with tryptase β and/or PRG4 are subjected to a quantitative shotgun proteomics and proteome changes are characterized, it further supports the role of NF-κB activation." (PMID 37024468, 2023). "This preclinical study of rhPRG4 in Prg4−/− mice offers our first insights into whether rhPRG4 shows activity in this inherited arthrosis in an orthologous animal model." (PMID 35457064, 2022). "PRG4 is involved in mediating TGF-β in osteoarthritis in mice." (PMID 33477984, 2021). "The evidence that this PG may act to attenuate friction-related joint degeneration is further corroborated by studies using different mouse models of osteoarthritis, in which disease progression could be prevented by PRG4 overexpression." (PMID 33199679, 2020). "Prg4 has been used to prevent surgically induced osteoarthritis (OA) in mice." (PMID 30629676, 2019). "Several other non-structural components with important cartilage ECM roles in development or osteoarthritis were also downregulated, including proteoglycan-related gene 4/lubricin (Prg4), procollagen C-endopeptidase enhancer 2 (Pcolce2), and Cytokine-like 1 (Cytl1)." (PMID 30793021, 2019). "PRG4 is known to change its expression in the case of acute cartilage tears as well as in the presence of chronic degenerative changes of hyaline cartilage, such as osteoarthritis." (PMID 27434644, 2016). "Here we have used an established ovine meniscectomy model of osteoarthritis, in which typical degenerative changes are observed in the operated knee joints at three months after surgery, to evaluate alterations in proteoglycan 4 expression and localisation in the early phases of the disease." (PMID 16469119, 2006). "However, the loss of the Grem1 lineage, but not the Prg4 lineage, led to histological features typical of osteoarthritis." (PMID 38891793, 2024). "However, transplantation for osteoarthritis or synovitis model could be required to confirm the treatment effect of iPSC-derived Prg4-expressing cells." (PMID 35870887, 2022). "Therefore, the condition media of Prg4-mRFP1 expressing cells could become an alternative regenerative agent against osteoarthritis and synovitis, and might also prolong the survival of Prg4-mRFP1 positive cell after transplantation." (PMID 35870887, 2022). "The homeostatic role of PRG4 in the joint is evidenced by the ability of purified native protein, recombinant full-length or truncated PRG4 to retard cartilage degeneration, enhance cartilage repair and reduce chondrocyte apoptosis in preclinical surgically induced osteoarthritis (OA) models." (PMID 26643105, 2015). "Proteoglycan 4 (PRG4), a secreted protein has also been explored as a potent chondroprotective factor in blocking the pathogenesis of osteoarthritis." (PMID 36246316, 2022).
osteoarthritis (continued). "Itga3 expression has been found to be downregulated in PBMCs from OA (osteoarthritis) patients, and a previous study has reported that the absence of Prg4 from the synovium leads to OA and aberrant fibroblast expansion and proliferation." (PMID 39235454, 2024). "Although PRG4 has been studied as a biomarker for diseases like chronic obstructive pulmonary disease, sepsis, osteoarthritis, and hepatocellular carcinoma, correlation between PRG4 levels and AVN has not been reported." (PMID 38825675, 2024). "Several non-clinical and clinical studies have shown that PRG4 and related molecules are promising candidates for disease-modifying drugs for treating osteoarthritis." (PMID 35501926, 2022). "In addition, studies using an antibody against the C‐terminal and N‐terminal of PRG4 protein showed its absence in CACP patient's synovial fluid, while it was detected in samples patients with rheumatoid arthritis and osteoarthritis." (PMID 29397575, 2018). "The TMJ of mature Prg4−/− mice has significantly increased OARSI (Osteoarthritis Research Society International) scores when compared to wild-type mice and, therefore, might be used in osteoarthritis modeling." (PMID 38891793, 2024). "Mice lacking the orthologous gene Prg4 may serve as an arthrosis model to understand the joint failure attributable to lack of PRG4 in humans, since many clinical features are recapitulated." (PMID 35457064, 2022). "For example, data suggest that PRG4 has anti-inflammatory effects (e.g. decrease in expression of a number of pro-inflammatory cytokines and matrix remodelling enzymes, in a CD44 and toll-like receptor 2- and 4-dependent manner) with implications for osteoarthritis, rheumatoid arthritis and gout." (PMID 31361756, 2019).
CACP syndrome (17 papers, 2008 to 2026). "Loss of function mutations in PRG4 are responsible for the autosomal recessive disease, Camptodactyly-Arthropathy-Coxa Vara Pericarditis (CACP) syndrome, a juvenile onset arthropathy." (PMID 39372933, 2024). "Healthy joints and some arthropathy syndromes caused by genetic mutations such as those in PRG4 gene (CACP syndrome) show very few immune cells in SF (unpublished, personal communications Wilkinson/Wedderburn)." (PMID 39101538, 2024). "Since identification of PRG4 as the causative gene for CACP syndrome, 36 PRG4 mutations have been reported." (PMID 36694203, 2023). "In this regard, we report two Azerbaijani siblings presented with chronic polyarthritis who was diagnosed initially juvenile idiopathic arthritis, and subsequently diagnosed with CACP syndrome with a novel mutation in the PRG4 gene is reported." (PMID 36694203, 2023). "Whole-exome sequencing was performed in both patients, which showed the existence of (to the best of our knowledge) a novel pathogenic (NM_005807.6):c.3445A > T(p.Lys1149Ter) homozygous mutation in the PRG4 gene associated with CACP syndrome." (PMID 36694203, 2023). "Herein, we report two siblings presented with chronic polyarthritis, had a prior diagnosis of juvenile idiopathic arthritis, but was subsequently diagnosed as CACP syndrome with novel mutation in the PRG4 gene." (PMID 36694203, 2023). "CACP syndrome is a rare recessive disorder (prevalence of < 1/1,000,000) caused by a mutation in the PRG4 gene coding for a lubricating proteoglycan of the surface of articular cartilage." (PMID 38001451, 2023). "The aim of presenting the 2 presented cases was to add a novel PRG4 mutation in the 2 sisters with CACP syndrome to the literature." (PMID 36694203, 2023). "We described the case of a girl affected by CACP syndrome caused by a novel compound heterozygous variant in proteoglycan 4 gene (c.2831_2832insT; c.3892C > T) and associated with temporomandibular involvement." (PMID 36545657, 2022). "Camptodactyly-arthropathy-coxa vara-pericarditis (CACP) syndrome is caused by a deficiency in PRG4 inherited as a recessive trait from both parents." (PMID 35457064, 2022). "Camptodactyly-arthropathy-coxa-vara-pericarditis (CACP) syndrome is an autosomal recessive disorder caused by mutations in PRG4 gene that encodes for proteoglycan 4, the main lubricant for joints and tendon surfaces." (PMID 28291008, 2017). "The importance of PRG4 to joint hemostasis is evidenced in the loss-of-function mutations in the Prg4 gene in the autosomal recessive disease, camptodactylyl-arthropathy-coxa vara pericarditis (CACP) syndrome, characterized by juvenile-onset arthropathy." (PMID 28482921, 2017). "The PRG4 gene is the only gene known to be associated with CACP syndrome." (PMID 36694203, 2023). "CACP syndrome is caused by mutations in the proteoglycan 4 (PRG4) gene." (PMID 36694203, 2023). "PRG4 is the only gene so far known to be associated with CACP syndrome." (PMID 27224999, 2016). "Children with CACP syndrome lack the glycoprotein lubricin due to recessive mutations in PRG4." (PMID 27224999, 2016). "The locus of CACP syndrome was allocated to a 1.9-cm interval on human chromosome 1q25-31 by homozygosity mapping, and proteoglycan 4 (PRG4) was identified as the responsible gene." (PMID 28291008, 2017).
rheumatoid arthritis (16 papers, 2015 to 2023). A chronic, systemic autoimmune disorder characterized by inflammation in the synovial membranes and articular surfaces. "This suggests that under inflammatory conditions such as rheumatoid arthritis, Prg4-expressing progenitors are shifted towards pathogenic fibroblasts." (PMID 36414376, 2023). "In patients with OA and rheumatoid arthritis (RA), PRG4 in the synovial fluid suppresses inflammatory responses." (PMID 35501926, 2022). "Proteoglycan 4 (PRG4), or lubrican, has been shown to promote an anti-inflammatory response in inflammatory osteoarthritis and rheumatoid arthritis." (PMID 33262757, 2020). "Furthermore, SF PRG4 levels decreased following acute joint trauma and in patients with advanced OA and rheumatoid arthritis (RA)." (PMID 32404156, 2020). "In human patients, serum PRG4 was unchanged in cases of rheumatoid arthritis (0.53 to 1.41 μg/mL, measured by ELISA) and advanced joint disease (0.25 to 1 μg/mL, measured by commercial ELISA kit), whereas plasma PRG4 was associated with joint space narrowing, after adjusting for age and sex." (PMID 33392293, 2020).
joint disease (12 papers, 2006 to 2025). "PRG4 loss of function, as seen in knockout mice (Prg4−/−), leads to degenerative joint changes recapitulating the phenotype of human camptodactyly-arthropathy-coxavara-pericarditis syndrome." (PMID 36444976, 2022). "Loss-of-function mutation of PRG4 in humans and Prg4 knockout in mice result in early-onset arthropathy accompanied by a decreased number of CSPCs." (PMID 35892602, 2022). "Prg4-knockout mice develop joint disease with age-associated increased joint friction and reduced mechanical properties of the cartilage." (PMID 22394585, 2012). "Limited studies are published on serum PRG4 concentrations within human subjects, and several examine its potential utility as a disease biomarker, particularly for joint disease." (PMID 33392293, 2020). "Homologs of lubricin—superficial zone protein, proteoglycan 4 (PRG4), megakaryocyte-stimulating factor precursor, and arthritis-like camptodactyly-arthropathy-coxa vara-pericarditis syndrome protein—are all encoded by PRG4." (PMID 25933137, 2015). "Prg4−/− mice appear normal at birth, but develop precocious clinical, radiologic, and histologic signs of joint disease as they age." (PMID 21905020, 2012). "Understanding the molecular regulatory mechanisms of Prg4 may provide insights into the pathophysiology of joint diseases and highlight potential therapeutic targets to enhance Prg4 expression to maintain joint health." (PMID 40149669, 2025). "CACP may also be considered an arthropathy that is partially inflammation mediated, as elucidated in animal models of Prg4 deficiency and as patients with CACP have used non-steroidal anti-inflammatory medications for pain relief." (PMID 35457064, 2022). "Camptodactyly-arthropathy-coxa vara-pericarditis (CACP) syndrome leads to diarthrodial joint arthropathy and is caused by the absence of lubricin (proteoglycan 4—PRG4), a surface-active mucinous glycoprotein responsible for lubricating articular cartilage." (PMID 35457064, 2022). "Collectively these findings suggest measurable changes to serum PRG4 concentration may lack specificity to joint disease." (PMID 33392293, 2020). "There is a large variability in the measured PRG4 levels of SF from patients with joint disease." (PMID 26037740, 2015). "Compared with heterozygous (Prg4+/−) mice, which do not develop joint disease, Prg4−/− mice exhibited an irregular surface with disruption of the normal, parallel orientation of collagen fibrils." (PMID 17968947, 2007).